RASGRF1 (Ras protein specific guanine nucleotide releasing factor 1)
Description:
Promotes the exchange of Ras-bound GDP by GTP.
Synonyms: Ras-GRF1; GNRP; CDC25; GRF1; CDC25L; GRF55; H-GRF55; PP13187
Tractability: Antibody: its Gene Ontology location is reachable by antibodies, with high confidence. PROTAC: UniProt records ubiquitination sites on it.
Gene: Protein-coding gene on chromosome 15 (78,959,906 to 79,090,780, reverse strand). Ensembl gene ENSG00000058335.
Subcellular location (Human Protein Atlas): Golgi apparatus
Pathways (Reactome):
Neuronal System: Ras activation upon Ca2+ influx through NMDA receptor
Signal Transduction: RAF/MAP kinase cascade
Gene Ontology:
Molecular function: guanyl-nucleotide exchange factor activity; glutamate receptor binding
Biological process: response to endoplasmic reticulum stress; long-term memory; negative regulation of MAPK cascade; neuron projection development; positive regulation of MAPK cascade; positive regulation of Rac protein signal transduction; positive regulation of Ras protein signal transduction; Ras protein signal transduction; regulation of Ras protein signal transduction; regulation of synaptic plasticity; signal transduction; intracellular signal transduction; small GTPase-mediated signal transduction
Cellular component: cytosol; growth cone; neuron projection; plasma membrane
Genetic constraint (gnomAD): Loss-of-function variants: 36 observed, 135.76 expected, observed/expected ratio (o/e) 0.27, 90% interval 0.2 to 0.35. The upper end of that interval is the gene's LOEUF score, 0.35, which puts it in group 1 of 6, group 1 being the genes least tolerant of losing a copy. Missense variants: 1,091 observed, 1,667 expected, observed/expected ratio (o/e) 0.65, 90% interval 0.62 to 0.69. Synonymous variants: 605 observed, 677.01 expected, observed/expected ratio (o/e) 0.89, 90% interval 0.83 to 0.96.
Homologues: Orthologues: chimpanzee RASGRF1 (99% identical), macaque RASGRF1 (99% identical), pig RASGRF1 (98% identical), dog RASGRF1 (97% identical), guinea pig RASGRF1 (97% identical), zebrafish rasgrf1 (89% identical), mouse Rasgrf1 (84% identical), rat Rasgrf1 (83% identical), tropical clawed frog rasgrf1 (82% identical), rabbit RASGRF1 (81% identical). Paralogues in human: RASGRF2 (67% identical), RAPGEF6 (16% identical), RAPGEF2 (16% identical), SOS2 (15% identical), SOS1 (15% identical), RAPGEF1 (13% identical), RAPGEF4 (12% identical), RAPGEF3 (11% identical), RAPGEF5 (10% identical), RALGDS (10% identical), RASGRP3 (9% identical), RASGEF1B (9% identical), and 12 more.
Diseases named in the same sentence as RASGRF1 in open-access papers:
RASGRF1 is named in the same sentence as 62 diseases in open-access papers, as found by Europe PMC text mining. Sharing a sentence is not in itself a finding about the gene and the disease. The quoted sentences say what the papers report.
myopia (14 papers, 2011 to 2024). "A key gene in the Ras signaling pathway, RASGRF1, has been associated with myopia, and there is evidence that its downstream pathway, the MAPK pathway, is differentially regulated in myopic retinas." (PMID 39876870, 2024). "We investigated the single nucleotide polymorphisms (SNPs) of the GJD2 and RASGRF1 genes, to explain the significance of these genes for refractive errors by dividing refractive disorders into myopia, hyperopia, and astigmatism." (PMID 35885949, 2022). "The RASGRF1 gene is thought to be associated with high-grade myopia, and we also believed that high-grade myopia should be significant in the results." (PMID 35885949, 2022). "Our findings suggest that PTPN5 rs1550870 and RASGRF1 rs6495367 are associated with the susceptibility to myopia and changes in several ocular parameters in southern Chinese children." (PMID 34122509, 2021). "To date, there have been many studies investigating the association between SNPs in RASGRF1 and myopia." (PMID 34122509, 2021). "In another GWAS involving 3,269 Japanese participants, the association between RASGRF1 and myopia was confirmed." (PMID 34122509, 2021). "Intriguingly we observed an association of DNA methylation with myopia at 7 at a CpG site within 100 bp of a RASGRF1 transcription start site." (PMID 31659193, 2019). "This included an association of myopia at 7 with DNA methylation at CpG site cg13403566 near RASGRF1 (uncorrected p = 6.4 × 10−5)." (PMID 31659193, 2019). "The aim of our research was to find associations between the GJD2, RASGRF1 genes and myopia development and to assess the heritability of myopia in Lithuania." (PMID 29793445, 2018). "We detected significant associations between the combinations of GJD2 CC and RASGRF1 GT and odds ratio of developing myopia." (PMID 29793445, 2018). "A recent study indicated that genetic variants in BICC1 and RASGRF1 are closely associated with high myopia, which appears to be a potential candidate for high myopia in a Chinese Han population." (PMID 29576878, 2018). "The studies of genetic associations in some European and Japanese populations showed that common genetic variations located in GJD2 and RASGRF1 were associated with common myopia and refractive error." (PMID 29793445, 2018). "But carriers of GT allele on the RASGRF1 gene had more risk to have myopia than carriers of wild type alleles." (PMID 29793445, 2018). "This association of the RASGRF1 gene with myopia was confirmed in a genome-wide meta-analysis that included 27 studies." (PMID 24808846, 2014). "In humans, a genome-wide association study (GWAS) identified single nucleotide polymorphisms (SNPs) in the RASGRF1 gene region on Chr 15q25 to be associated with myopia and refractive error." (PMID 24808846, 2014). "Also, results of meta-analysis, which included 2529 individuals with high-degree myopia and 3127 controls, showed that RASGRF1 was significantly associated with high-degree myopia in Chinese and Japanese populations." (PMID 29793445, 2018). "But we found significant association between the combinations of GJD2 CC and RASGRF1 GT and myopia." (PMID 29793445, 2018). "However, carriers of the RASGRF1 G allele had a lower risk of high-degree myopia compared to carriers of the T allele (G versus T)." (PMID 29793445, 2018). "We found a significant association between combinations of GJD2 and RASGRF1 genotypes and myopia." (PMID 29793445, 2018). "Taken together, our results provide evidence for a role of the RASGRF1 gene locus in hippocampus-dependent memory and, along with the previous association with myopia, point toward pleitropic effects of RASGRF1 genetic variations on complex neural function in humans." (PMID 24808846, 2014). "RASGRF1 rs8027411 was first identified in a GWAS of myopia as a risk locus." (PMID 24808846, 2014).
myopia (continued). "Also in humans, a genome-wide association study has identified the single nucleotide polymorphism (SNP) rs8027411 in the putative transcription regulatory region of RASGRF1 as a risk variant of myopia." (PMID 24808846, 2014). "Rasgrf1 upregulation has been found in the sclera of myopic eyes; however, further investigation is needed to determine whether Rasgrf1 plays a causative role or whether it is a consequence of myopia‐induced scleral remodeling." (PMID 39207058, 2024). "Moreover, with RASGRF1 rs8027411 having been linked to myopia, our findings also provide an example for the same genetic variant exerting pleiotropic effects at systems level and thereby conferring both advantageous and disadvantageous effects on distinct complex phenotypes." (PMID 24808846, 2014). "Moreover, RASGRF1 gene in 15q25 is considered to be the susceptibility gene, and it is involved in learning, visual processing and muscarinic signaling pathways, all of which are considered to be correlated with myopia." (PMID 24767175, 2014). "In our previous studies, we investigated the association of these genes with myopia and found significant associations with combinations of GJD2 (rs634990) and RASGRF1 (rs8027411) genotypes." (PMID 35885949, 2022). "As the first two susceptibility loci found to be associated with myopia, GJD2 and RASGRF1 were significantly associated with HM in those with HM and MMD in the current study and previous studies." (PMID 31415580, 2019). "As the expression and role of GJD2 and RASGRF1 in eye and myopia development have been explored and reported previously, we focused on the gene expression of KCNMA1 in human ocular tissues." (PMID 31415580, 2019). "Our study showed that individuals with combinations of GJD2 CC and RASGRF1 GT genotypes were 2.7 times more likely to have myopia (p = 0.046)." (PMID 29793445, 2018). "Another evidence of knockdown model indicating that RASGRF1 is contributed to myopia is that knockdown mouse models remain normal brain structure but have worse performance in exercises including long-term memory than wild-type mice." (PMID 24767175, 2014). "Above all, RASGRF1 appears to be related in the maintenance of normal function of the retina and possibly in the signaling pathways determining myopia." (PMID 24767175, 2014). "Three genes for myopia, in 15p14 (GJD2, ACTC1) and 15q25 (RASGRF1), were identified to be susceptible loci in European Caucasians." (PMID 23649821, 2013). "Of interest in terms of imprinted genes and myopia is RASGRF1." (PMID 31659193, 2019). "We also evaluated the roles of RASGRF1 rs6495367, PDGFRA rs6554163, and PTPRR rs11178469 in myopia in a southern Chinese Han population." (PMID 34122509, 2021). "This study aimed to assess heritability of myopia in Lithuania and evaluate both genes GJD2 (Gap Junction Protein, Delta 2) and RASGRF1 (RAS protein-specific guanine nucleotide-releasing factor 1) relation with myopia." (PMID 29793445, 2018). "The odds ratio of myopia compared to emmetropia (95% confidence intervals [CIs]) was 2.7 (1.018–7.460) for GJD2 CC and RASGRF1 GT genotypes." (PMID 29793445, 2018). "By revealing the potential relationships between genes and miRNAs correlated with PDGFRA, RASGRF1, and PTPN5, this study may shed new light on myopia at the molecular level." (PMID 34122509, 2021).
rheumatoid arthritis (4 papers, 2009 to 2025). A chronic, systemic autoimmune disorder characterized by inflammation in the synovial membranes and articular surfaces. "RasGRF1 was significantly enhanced in rheumatoid arthritis synovial tissue, and it contributed to Matrix metalloproteinase-3 (MMP-3) production." (PMID 35740904, 2022). "A recent study has found that RasGRF1 in synovial fibroblasts regulates the inflammatory process by producing matrix metalloproteinases (MMPs) that destroy the joint structure in rheumatoid arthritis." (PMID 30308936, 2018). "In the rheumatoid arthritis, RasGRF1 has been found to contribute to the production of matrix metalloproteinases by regulating inflammation processes." (PMID 30308936, 2018). "Consistent with our data, the increased expression of RasGRF1 also has been found in rheumatoid arthritis and aging-related cardiac fibrosis." (PMID 30308936, 2018).
Arthritis (3 papers, 2009 to 2025). Inflammation of a joint. "Identification of the protease(s) responsible for RasGRF1 cleavage in vivo may lead to new therapeutic strategies in the treatment of arthritis." (PMID 19678938, 2009). "Moreover, RASGRF1 and NLRP3 protein expression was lower in the synovial tissue of the IGF2BP3-KO arthritis mice than in that of the WT arthritis mice." (PMID 40355406, 2025). "In addition, the protein expression levels of RASGRF1 and NLRP3 were reduced by CEL in WT arthritis mice." (PMID 41164801, 2025).
colorectal cancer (3 papers, 2009 to 2020). A primary or metastatic malignant neoplasm that affects the colon or rectum. "RASGRF1 is a guanine nucleotide exchange factor, which promotes the release of GDP from inactive Ras and stabilizes the apoprotein; its hypermethylated status was found to be a potential risk factor for colorectal cancer, in experiments performed in rats." (PMID 33194559, 2020). "Hypermethylation of RASGRF1, has been suggested as a biomarker for colorectal cancer." (PMID 32735660, 2020).
melanoma (3 papers, 2009 to 2025). A malignant, usually aggressive tumor composed of atypical, neoplastic melanocytes. "Recent evidence has shown that expression levels of the GEF RasGRF1 regulate constitutive MMP-9 production in human melanoma cells." (PMID 19678938, 2009). "We and others recently reported a distinct class of oncogenic fusions involving the RAS-GEF RASGRF1 in NSCLC, pancreatic ductal adenocarcinoma (PDAC), melanoma, and sarcoma." (PMID 40615519, 2025). "We identified 17 RASGRF1 fusions, including 5 in NSCLC, 3 in melanoma, and 1 in PDAC." (PMID 40615519, 2025). "RasGRF1 specifically activates H-Ras, but not other Ras homologs in vivo, and RasGRF1 activation of H-Ras induces constitutive MMP-9 production in human melanoma cells." (PMID 19678938, 2009). "In addition to RASGRF1 fusions, analogous rearrangements involving the related RAS-GEF RASGRF2 have been reported in melanomas and melanocytic neoplasms lacking known driver alterations." (PMID 40615519, 2025).
breast carcinoma (2 papers, 2020 to 2023). "Most of these genes were associated with cancers of metabolic systems (DUSP6, SGK1, BMP4, RASGRF1, GDF15) followed by breast cancer (CACNA2D3, ITGB7), cancers of the central nervous system (PRKCA), or leukemia (MECOM, JAK3)." (PMID 36624125, 2023). "Among the 4 genes, RASGRF1 and CPXM1 represented common breast cancer marker, while HOXA10 and DACH1 represented luminal-dominant marker and triple negative dominant marker, respectively." (PMID 32550045, 2020). "It is interesting to mention that four methylation markers (RASGRF1, CPXM1, HOXA10, and DACH1) in circulating cell-free DNA could discriminate cancer from normal with high sensitivity (0.86) and specificity (0.83) in early breast cancer." (PMID 32550045, 2020).
cancers of the central nervous system (2 papers, 2023). "Nomogram and calibration curves further confirmed that the prognostic model composed of SYT1, CREB3L3, ITPR1, RASGRF2, PDX1, and RASGRF1 has good stability and potential application value for poor prognosis in patients with glioma." (PMID 37090987, 2023). "The LASSO regression model was constructed to screen the molecular models related to glioma prognosis, which were composed of SYT1, CREB3L3, ITPR1, RASGRF2, PDX1, and RASGRF1." (PMID 37090987, 2023). "Interestingly, the imbalance of oxidative stress-related pathways was also exhibited in glioma tissues, and the expression of SYT1, CREB3L3, ITPR1, RASGRF1, RASGRF2, and PDX1 were significantly different from that of para-cancerous tissues." (PMID 37090987, 2023).
diabetic cardiomyopathy (2 papers, 2018 to 2025). Diabetic cardiomyopathy is a disorder of the heart muscle in people with diabetes. "RasGRF1 activity enhances cardiac fibrosis in the aging mouse heart as well as increasing ECM deposition in the myocardium during diabetic cardiomyopathy." (PMID 39793891, 2025). "Although it is known that inflammatory processes and oxidant stress via ER are still the major mechanisms of diabetic cardiomyopathy, it is still unclear whether RasGRF1 also regulates the long-term diabetic condition-induced cardiac fibrosis." (PMID 30308936, 2018).
gastric cancer (2 papers, 2016 to 2022). A primary or metastatic malignant neoplasm involving the stomach. "Hypermethylation in the promoter region of RASGRF1 has been observed in gastric cancer cells and precancerous tissues of the gastric mucosae." (PMID 27993161, 2016). "Furthermore, increased methylation of RasGrf1 in the gastric mucosa of patients with gastric cancer has been observed as compared with healthy individuals, which results in a low expression of RasGrf1 as well as tumor invasion." (PMID 35855334, 2022).
lung adenocarcinoma (2 papers, 2025). A carcinoma that arises from the lung and is characterized by the presence of malignant glandular epithelial cells. "Finally, using the TCGA clinical cohort, we identified that high expression of RASGRF1 significantly prolongs the OS of lung adenocarcinoma (LUAD) patients; RASGRF1 is a gene involved in the inflammatory response." (PMID 40786043, 2025). "We and others also previously reported RASGRF1 fusions in 2 additional lung adenocarcinomas from individuals with no smoking history without a known driver." (PMID 40615519, 2025).
adenoma (1 paper, 2017). A neoplasm arising from the epithelium. "Genes associated with the recurrent gained VELs shared between CRC and the adenomas included FOXQ1 and RASGRF1 (right)." (PMID 28169291, 2017).
asthma (1 paper, 2025). "In the female EWAS, genes well known to be linked with asthma include MUC1, RASGRF1 and IL9138." (PMID 40410506, 2025).
astrocytoma (1 paper, 2023). "Previous studies showed that RasGRF1 could be regulated by miR-137 to inhibit astrocytoma." (PMID 37053022, 2023).
bipolar disorder (1 paper, 2022). A disorder of the brain that causes unusual shifts in mood, energy, activity levels and the ability to carry out day-to-day tasks. "Consistently, it has been shown that Rasgrf1 knockdown reversed the effect of UCMS on mice, and it has been shown in humans that RASGRF1 may be a potential specific biomarker of treatment response for bipolar disorder." (PMID 36362329, 2022).
bladder cancers (1 paper, 2025). "Some were identified from tumors in which RASGRF1 fusions have not previously been reported, including cholangiocarcinoma, colorectal, gastroesophageal, and bladder cancers." (PMID 40615519, 2025).
Blindness (1 paper, 2017). Blindness is the condition of lacking visual perception defined as a profound reduction in visual perception. "Of 50 genes with high impact variants, only three genes (RASGRF1, IQCB1 and CCDC114) had been previously associated with blindness." (PMID 28322220, 2017).
Cognitive impairment (1 paper, 2023). Abnormal cognition is characterized by deficits in thinking, reasoning, or remembering. "Therefore, in this study, we investigated RasGRF1 levels after CCH to explore the underlying mechanisms of CCH-induced cognitive impairment and to determine new effective therapeutic targets." (PMID 37053022, 2023). "Overall, RasGRF1 regulation attenuated cognitive impairment, helped maintain structural and functional synaptic plasticity, and prevented synapse deterioration after CCH." (PMID 37053022, 2023). "Meanwhile, Rasgrf1 upregulation via miRNA-323-5p inhibition may ameliorate cognitive impairment by promoting synaptic plasticity, providing a potentially valuable and effective therapeutic target for cognitive dysfunction after CCH." (PMID 37053022, 2023). "This RasGRF1 regulation could improve cognitive impairment, functional and structural synaptic plasticity, and synapse deterioration after CCH." (PMID 37053022, 2023). "Thus, RasGRF1 and miRNA-323-3p may represent potential therapeutic targets for cognitive impairment after CCH." (PMID 37053022, 2023). "However, whether RasGRF1 contributes to cognitive impairment after CCH remains to be determined." (PMID 37053022, 2023). "Thus, this indicates that RasGRF1 downregulation may contribute to the reduction in structural plasticity and subsequent cognitive impairment after CCH, and RasGRF1 upregulation could improve them." (PMID 37053022, 2023).
depression (1 paper, 2022). "The NMDA subtype of glutamate receptors (NMDAR) plays a key role in synaptic plasticity in the context of depression, and it has been shown that a Ca2+/calmodulin-dependent Ras-guanine-nucleotide-releasing factor (RasGRF1) served as an NMDAR-dependent regulator of the ERK kinase pathway." (PMID 36362329, 2022).
diabetes (1 paper, 2018). "Streptozotocin (STZ) (50 mg/kg body weight) was injected consecutively for five days to induce diabetes mellitus in WT (wild-type) B6 and RasGRF1 deficiency (RasGRF1−/−) mice." (PMID 30308936, 2018). "This study demonstrates that a long-term diabetes condition can upregulate the RasGRF1 expression in heart tissue." (PMID 30308936, 2018). "The diabetes WT mice showed significant upregulation of MCP-1 and fibronectin-positive cells compared to the control group and the RasGRF1−/− group." (PMID 30308936, 2018).